GZMB (granzyme B)
Diseases named in the same sentence as GZMB in open-access papers (continued):
Sharing a sentence is not in itself a finding about the gene and the disease.
tumor (continued). "Furthermore, the anti-tumor function of granzyme B+ B cells in tumor samples was adversely affected, potentially providing an explanation for tumor progression." (PMID 38386050, 2024). "However, patients treated with C7R-GD2.CARTs exhibited a higher proportion of tumor-specific polyfunctional cells as well as circulating IFN-γ and granzyme B levels, which have been associated with improved tumor killing by T cells." (PMID 38771986, 2024). "Furthermore, we observed an increase in Granzyme-B+CD8+ T cells in the tumor parenchyma in DOX+GLUT1i treated mice relative to the single treatments, suggesting that the combinatorial treatment promotes T-cell activation and cytotoxicity." (PMID 38509063, 2024). "Moreover, treatment with Nb‐TriTE alone did not induce the secretion of cytolytic molecules, perforin, and granzyme B, in mouse serum and in xenograft tumor area." (PMID 39234811, 2024). "Moreover, studies on isolated brain samples showed increased levels of NKp46+ and granzyme B+ NK cells in mice treated with synNotch iNK cells, indicating an enhanced functional activation of NK cells at tumor sites." (PMID 39339180, 2024). "However, after the 2nd dose, the total number of CD8+ T cells in the tumor environment significantly increased, and the expression levels of Granzyme B, CD107a, and perforin increased." (PMID 38554184, 2024). "Studies have demonstrated that the bioactive compounds of TCM, such as anthraquinones, plant-extracted glycoproteins and terpenes, can enhance tumor immune surveillance by inducing the secretion of perforin and granzyme B, boosting the proliferation ability and self-function of NKs." (PMID 38792234, 2024). "However, areas of diffuse immune infiltration had more cytolytic activity as indicated by higher Granzyme B in immune segments, as well as higher tumor expression of targetable checkpoints PD-L1, Tim-3, and IDO1." (PMID 39026018, 2024). "Furthermore, the CEP55 knockout increased CD8+ T cell infiltration and granzyme B production, indicating improved anti-tumor immunity." (PMID 38250876, 2024). "While we did not observe the same skewing of macrophages toward M1 TAMs or more mature DCs in our BPR model, we did note an increase in cytotoxic Granzyme B+ CD4+ T cells known to mediate direct killing of MHC II+ tumor cells, as well as an increase in central memory CD4+ and CD8+ TIL." (PMID 38312842, 2024). "Additionally, TNF-α and Granzyme B-producing populations were also increased in the tumor antigen-specific CD8+ T cells by HK-C60 administration." (PMID 38792006, 2024). "Studies show that intratumoral administration of a CXCL11-armed tumour selective vaccinia OV increases tumour-specific CTLs and granzyme B production, while reducing immunosuppressive cytokines in the TME of a syngeneic mouse mesothelioma model, leading to enhanced cytotoxic activities of CTLs." (PMID 39450176, 2024). "Additionally, the ratio of IFN-γ+, TNF-α+, or GZMB+ in tumor-infiltrating CD8+ T cells was decreased in MC38 tumors on Vegfb-cKO mice, whereas the cytokine production in these cytokine+ cells was not affected." (PMID 39145452, 2024). "Studies have indicated that CD8+ T cells infiltrate tumor lesions by secreting granzyme B, which promotes the remodeling of the BMs of tumor blood vessels, facilitating their migration that means BMs may be related to the immune microenvironment in HCC." (PMID 38870261, 2024). "Additionally, it sensitizes tumor cells to CAR-T cell activity by promoting granzyme B penetration into tumor cells." (PMID 38727261, 2024). "Similarly, granzyme B (GZMB) from these immune cells can also initiate GSDME-dependent apoptotic cell death in tumor cells through caspase-3-mediated cleavage of GSDME." (PMID 39723212, 2024).
tumor (continued). "Activated CTLs kill target tumor cells mainly through two pathways: first, CTL release perforin (PFN) to transport secreted granzymes A and B (GzmA and GzmB) into tumor cells after forming pores in the tumor cell membrane, triggering an enzyme chain reaction that leads to apoptosis of tumor cells." (PMID 38270700, 2024). "Conversely, immune activity-related signatures, including PRF1, GNLY, GZMA, GZMB, and interferon regulatory factor 1, play crucial roles in tumor cell recognition and tumoricidal, with connections to extended survival, and identifying responders to anti-PD-1 antibody treatment." (PMID 38956740, 2024). "Anti-mOPN alone reduced tumor growth along with an increase in CD3 + CD8+ granzyme B + T cell." (PMID 39448577, 2024). "Stimulation with a commercial T cell activation kit led to increased granzyme B expression in tumor cells, heightened granzyme B release into culture supernatants, and upregulated pro-apoptotic cleaved caspase 3 in tumor cells under control conditions, aligning with previous publications." (PMID 38515569, 2024). "In addition, the frequency of IFN-γ and Granzyme B producing CD8+ T cells in the tumor was increased." (PMID 39114660, 2024). "As an increase was observed in the number of tumor‐infiltrating Granzyme B+ cells in C1galt1 knockout tumors, we further performed ex vivo CTL assays to elucidate whether the T cell‐mediated cytotoxicity was involved." (PMID 37452653, 2024). "GZMB has been identified as a cytotoxic T lymphocyte (CTL) marker that induces tumor apoptosis." (PMID 38245530, 2024). "On the contrary, in metastatic tumours of mice deficient in HStC STAT3 (STAT3cKO), we observed an increase in the number of infiltrating CD8+ T cells and an increase in their activation state (GzmB+)." (PMID 38678021, 2024). "Furthermore, the injection of LNCs@CSF1R siRNA increased the production of effector cytokines IFNγ and GzmB by CD8 + T cells within the tumor." (PMID 38992688, 2024). "In contrast to total CD8+ T cells, which had the highest accumulation in the 0- to 200-μm peritumoral region, the largest density of CD8+ GzmB+ T cells was observed in the 0- to 200-μm intratumoral region on D14, suggesting antitumor cytolytic activity at the tumor border." (PMID 38518770, 2024). "Furthermore, expression of the cytotoxic protein granzyme B and cytokine secretion were robustly and specifically induced upon tumor engagement." (PMID 38561797, 2024). "Notably, granzyme B derived from carcinoma sources has been observed to effectively eliminate tumor cells in vitro." (PMID 38533507, 2024). "Furthermore, the combination treatment significantly augmented the production of cytotoxic molecules, including Granzyme B, Perforin, and TNFα, in both primary and distant tumor‐infiltrating CD8+T cells." (PMID 38308189, 2024). "The inhibition of this interaction results in the activation of Bax by truncated Bid at the mitochondrial membrane, which facilitates the GzmB-induced increase in mitochondrial outer membrane permeability, thereby expediting the pro-apoptotic effect of NK cells on tumor cells." (PMID 39185404, 2024). "Therefore, we then analyzed the function of tumor-infiltrating T cells and found that TREM2 inhibited T cell-mediated secretion of anti-tumor molecules, including granzyme B and perforin." (PMID 39135069, 2024). "Moreover, tumor-infiltrating CD8+ T cells and NK cells in TREM2-deficient mice were more capable of secreting perforin and granzyme B, and GB1107 treatment further enhanced it." (PMID 39135069, 2024). "In tumor cells, NK cells can either directly kill the tumor cells through their cytotoxicity or indirectly destroy them through the secretion of cytotoxic mediators such as granzyme B(GzmB) and perforin." (PMID 39185404, 2024). "GzmB, which functions through caspase-dependent and independent mechanisms, is a powerful pro-apoptotic enzyme employed by CTLs and NK cells to destroy infected or tumor cells." (PMID 38629077, 2024).
tumor (continued). "We repeated the experiment and determined the relative quantity of granzyme B in target tumor cells (A375-NY-GFP) using FACS to make clear whether tumor cells were being attacked by T cells." (PMID 38672132, 2024). "Moreover, the expression of the critical downstream mediator of IRE1α pathway, XBP1, was also highly associated with the mRNA levels of the indicators of lymphocytes and anti-tumor immunity, including PTPRC (encoding CD45), CD8A, GZMB and IFNG." (PMID 38291473, 2024). "Disruption in GZMB activity could be correlated with diminished entry, trafficking, and accumulation within the cytoplasm of target cells, such as tumor cells." (PMID 39329702, 2024). "B cells actively induce tumor cell apoptosis by producing granzyme B, a potent cytolytic molecule." (PMID 38533507, 2024). "Consistently, the loss of HER2 on the knockout tumor cells led to dramatically reduced T cell secretion of IFN-λ and granzyme B in the presence of the HER2-CD3-Fc bsAb, indicating that HER2 binding was required for the bsAb-mediated cytotoxic T cell activation." (PMID 39066446, 2024). "Our analyses also showed a negative correlation between the mean expression of granzyme B in conventional cytotoxic NK cells and the grade of the disease (R = −0.42), which collectively suggest the decrease in the level of granzyme B expression in patients by the progression of the tumor." (PMID 38652012, 2024). "To analyze whether the bsAb mediated T cell activation in response to the tumor cells, we measured the levels of the effector molecules granzyme B, IFN-λ, and TNF-α secreted into the medium by T cells." (PMID 39066446, 2024). "Similarly, the mRNA-LNPs strongly promoted T-cell-dependent killing and secretion of IFN-λ, TNF-α, and granzyme B against other HER2-positive tumor cells, including NCI-H460, SKOV-3, and MDA-MB-231." (PMID 39066446, 2024). "IL-33 also has a role in the anti-tumour response to melanoma by not only increasing the secretion of INFγ and granzyme B from CD8+ T and NK cells as well as proliferation of CD4+ T cells but also reducing the differentiation of PMN-MDSCs from bone marrow cells." (PMID 38893071, 2024). "In addition, by immunohistochemistry staining, there was also remarkably less infiltration of CD8 positive and granzyme B positive immune cells in the tumor tissues developed from CT26-CD45 than CT26-Vector cells." (PMID 38575583, 2024). "It collaborates with GZMB and perforin as a cytotoxic cytokine to trigger apoptosis in tumor cells." (PMID 39329702, 2024). "Tumor tissues of mice were taken and made into pathological sections, and the functional biomarkers that can reflect T cell activation, such as Cd8, Tbx21 and Granzyme B, were detected by immunohistochemistry." (PMID 38231305, 2024). "Moreover, the density of tumor-infiltrating CD11c+ DCs and GzmB+ T cells was significantly increased in the RT plus TLC388 group." (PMID 38564022, 2024). "In addition, cleavage of GSDME by GZMB promotes tumour cell death and enhances the establishment of anti‐tumour immune effects." (PMID 38652105, 2024). "Thus, radiopharmaceuticals that monitor the activity of granzyme B have the potential to monitor active T cell-mediated anti-tumor activity in real-time." (PMID 39104861, 2024). "These effector T cells from PBMCs treated with CD3 and CD28 antibodies could secrete IFN-γ and TNF-α to act as cytotoxic cytokines together with granzyme B and perforin to initiate apoptosis in tumor cells, thereby killing cancer cells." (PMID 38321486, 2024).
tumor (continued). "Since granzyme B activity measurement was unsuitable for detecting T cell-mediated tumor cell killing, we set up an in vitro cytotoxicity assay based on crystal violet staining of adherent tumor cells." (PMID 39075115, 2024). "In summary, our results showed that LZFPN-90 could promote T-cell proliferation, activate CD8+ toxic T cells, and enhance the secretion of IFN-γ and GzmB, thereby killing tumor cells." (PMID 38448544, 2024). "Interestingly, the granzyme B production in the smokers was overall lower compared to the control and even compared to the tumor group." (PMID 38650948, 2024). "In contrast, tumors from surviving patients at 5-year postdiagnosis exhibited low, sporadic tumor NOS2/COX2 expression and elevated CD8+ T-cell infiltration into the tumor, which promotes tumor eradication by perforins and granzyme B in a cell-to-cell contact manner." (PMID 39356141, 2024). "It is hypothesized that GZMB is necessary for the induction of apoptosis in tumor cells and is synonymous with T cell cytotoxicity." (PMID 38307835, 2024). "Moreover, qRT-PCR results revealed significant upregulation of CD27, CXCL13, IFNG and GZMB in tumor-specific T cells using." (PMID 39033098, 2024). "Adding CD3xTRP1 treatment resulted in the emergence of a population of highly activated OT-1 T cells in the tumor, reflected by a significant upregulation of intracellular GzmB expression, and high expression of multiple activation markers, such as 4-1BB, CD27, NKG2A, PD-1 and Tim3." (PMID 38167722, 2024). "In addition, the later adaptive immune response, dominated by CD40 and PD‐L1, suggests active reprogramming of the tumor environment and evolution of adaptive immunity, possibly supported by the IL‐17 response and Granzyme B to mediate apoptosis." (PMID 38553868, 2024). "Besides IFN-γ, TNF-α, perforin, and Granzyme B production were elevated upon treatment of PD-L1-expressing tumor cells and primary T cells with pentamidine." (PMID 37205112, 2023). "Importantly, the amount of granzyme B(+) immune cells was also significantly increased in the TME in mice bearing the A20-knockdown tumor." (PMID 37607946, 2023). "Taken together, FSS impairs conjugate formation between NK and tumor cells while promoting NK cell activation and the delivery of granzyme B into target cells within the conjugates, which may enhance NK cell's cytotoxicity." (PMID 37575881, 2023). "In the α4-1BB/AlloDC combination group, we observed an overall higher infiltration of CD8 T-cells, especially TRM, which was shown to control tumor growth by producing granzyme B and IFN-γ for the direct killing of tumors, eliciting the production of chemokines and expression of adhesion molecules." (PMID 37654492, 2023). "Additionally, B cells possess the capacity to directly eliminate tumor cells through the secretion of the cytotoxic enzyme, granzyme B." (PMID 38066437, 2023). "Notably, Cxcr3 blockade interfered with the frequency of splenic engineered T cells that expressed Granzyme B (GzmB), paralleling the defect in endogenous GzmB + tumor-specific T cells in Cxcr3−/− mice." (PMID 36472588, 2023). "Moreover, an increased number of infiltrated CD8+ T cells and stronger granzyme B signals were detected in tumor sections isolated from mice treated with both 6J1 and anti‐PD‐1 antibody, when compared to those from mice treated with 6J1 or anti‐PD‐1 antibody." (PMID 36567273, 2023). "Furthermore, the combination of TH-302 NPs with α-PD-1 significantly promoted the levels of TNF-α, IFN-γ, and granzyme B in tumour tissues." (PMID 37993847, 2023). "Importantly, upregulated IL‐1β expression was associated with attenuated cytotoxicity of CAR‐T cells and reduced CD8+granzyme B distribution in patient‐derived tumor tissues." (PMID 37009412, 2023).
tumor (continued). "CD8+ cytotoxic T cells recognize tumor cells displaying tumor antigens bound to major histocompatibility complex class I (MHC‐I)/human leucocyte antigen (HLA) proteins and kill tumor cells by producing cytotoxic effector molecules, such as granzyme B and tumor necrosis factor α (TNFα)." (PMID 37452654, 2023). "Moreover, PD-1-containing EVs also directly attacked tumor cells via Fas-ligand (FasL) and granzyme B (GzmB)." (PMID 37686050, 2023). "Lastly, we sought to explore whether a significantly increased expression of granzyme B in the tumor periphery correlates with disease progression." (PMID 37894418, 2023). "In addition, depletion of Id1 in TAMs increased the expression of interferon-γ (IFN-γ) and Granzyme B in tumor-infiltrating CD8+ T cells." (PMID 37996458, 2023). "To identify biomarkers of these cells, we investigated granzyme B (GZMB) in the tumor microenvironment as a biomarker of treatment response and prognosis in 230 patients with primary TNBC who underwent surgery without preoperative chemotherapy between January 2004 and December 2014." (PMID 37760424, 2023). "Similarly, in colorectal cancer intraepithelial T-bet+EOMES+ ILC1s produced IFN-γ and expressed granzyme B and perforin which can inhibit tumor growth." (PMID 38567059, 2023). "The relationship between Granzyme B expression and tumor stage has also been suggested." (PMID 37532996, 2023). "In addition, Teffs are critical for antitumor immunity as tumor‐killing executors, and their marker, GZMB, is one of the components of the IPS." (PMID 36998102, 2023). "Moreover, the combination strategy significantly promoted the infiltration of CD8+ CTL compared with shPES1 and anti-PD-1 administration alone and increased the percentage of GZMB+/CD8+ CTL in the tumor microenvironment." (PMID 36959575, 2023). "Alternatively, cytotoxic cells may fail to express granzyme B in the tumor environment, resulting in reduced NK cell and CD8+ T cell driven tumor cell killing." (PMID 37691935, 2023). "We could show with conventional immunohistochemistry that a significant upregulation of granzyme B in the tumor periphery was limited to a relatively small subset of tumors, while the majority may in fact represent tumors with mostly exhausted T cells." (PMID 37894418, 2023). "Also important was the observation that a first dose of FAP-CAR T cells enhanced the activation of CD45.2+tdTomato+ Meso-CAR T cells in tumor sites, as demonstrated by increased expression of GzmB, TNF-α, and IFN-γ after stimulation." (PMID 37607999, 2023). "In addition, pDCs directly induce tumor cell lysis via secreting cytotoxic cytokines including granzyme B (GZMB), TNF-α, and soluble TRAIL85." (PMID 37817484, 2023). "Meanwhile, the numbers of stem-like CD8+PD-1+TCF-1+ T cells, terminally exhausted CD8+PD-1+TCF-1- T cells and terminally exhausted CD8+ T cells secreting GzmB (CD8+PD-1+TCF-1-GzmB+ T cells) in tumor tissues were also remarkably enhanced in R848@M2pep-MPsAFP-treated group." (PMID 37704614, 2023). "Additionally, a greater fraction of lung gp33-specific CD8+ T cells expressed Granzyme B in treated mice, suggesting improved effector function within the tumor-specific CD8+ T cell population." (PMID 37794033, 2023). "NsPEF induced a greater number of cytotoxic CD8+ T cells producing Granzyme B in the tumor." (PMID 37046739, 2023). "Furthermore, these type 1 IFNs induce granzyme B (Gzm-B) expression in CD8+T cells by STAT3 activation to increase their cytotoxic action against tumor cells." (PMID 37380989, 2023). "In contrast, combined T/P and Taz treatment led to further increased T cell and NK cell infiltration and GZMB expression, culminating in tumor regressions in 8/17 of PDAC-bearing KPC GEMMs and significantly increased overall survival in the absence of a detectable apoptotic response." (PMID 37142692, 2023).